SIRT1 (sirtuin 1)
Diseases named in the same sentence as SIRT1 in open-access papers (continued):
Sharing a sentence is not in itself a finding about the gene and the disease.
cancer (continued). "SIRT1 is a member of the sirtuin family, which is involved in many diseases and bioprocesses such as cancer development, oxidative stress, and pyroptosis." (PMID 35355717, 2022). "Consistent with previous studies, our results suggested that SIRT1‐mediated deacetylation of FOXK2 reduced apoptosis in cancer cells." (PMID 34866322, 2022). "In the context of DNA damage, FOXO3 deacetylation‐mediated apoptosis is also attenuated, suggesting that SIRT1‐mediated deacetylation of FOXO proteins significantly reduces apoptosis in cancer cells." (PMID 34866322, 2022). "The vast literature demonstrated that SIRT1 expression increased in most human cancers, especially, prostate cancer, primary colon cancer, acute myeloid leukemia, and squamous epithelial cell carcinoma." (PMID 35548580, 2022). "In cancer, SIRT1 and SIRT6 act as tumor suppressors, whereas SIRT7 is responsible for tumor phenotype maintenance, and its expression is increased in many cancers." (PMID 36012298, 2022). "Since previous studies have found that AMPK regulates PGC-1α through p38 MAPK or Sirt1 in cancer cells and skeletal muscle, we further investigated the relationship between AMPK and PGC-1α in HC11." (PMID 35248054, 2022). "Cancer cells downregulate sirtuin-1 (SIRT-1), which destabilizes the mRNA of ATP6V1A, a subunit of the complex." (PMID 35050379, 2022). "A recent study found that some members of the sirtuin (Sit) family (Sirt1-7), which are mammalian homologs of the yeast silent information regulator (Sir2) gene, play important roles in cancer development." (PMID 36132133, 2022). "In the tumor microenvironment, both infiltrated immune cells and cancer cells can be affected by SIRT1." (PMID 35212616, 2022). "The role of SIRT1 and FoxOs as regulators in important signaling pathways in tumor progression suggests that they are closely related to cancer." (PMID 36142156, 2022). "SIRT-1 inhibitors have been investigated in prostate cancer as well: EX-527 increased the sensitivity of cancer cells to vesicular stomatitis virus oncolysis, while compound 17 (discovered by VS, see Section 3.1) exhibited anti-proliferative effects in vitro." (PMID 36080416, 2022). "The most studied SIRTs in cancer are SIRT-1, -2, -3 and -6, with modulators that either exhibit an anti-proliferative effect, induce apoptosis, or sensitize cancer cells to existing chemotherapeutics in vitro, or that block tumor growth in vivo." (PMID 36080416, 2022). "In this study, the mRNA of SIRT1 and its respective protein were markedly increased in all sensitive and resistant cancer cell lines following curcumin treatment." (PMID 36143462, 2022). "They revealed that RSV was able to activate Sirt1 and inhibit the expression of survivin leading to a greater inhibitory on Brca1 mutant cancer cells than on Brca1-wild-type cancer cells." (PMID 35327559, 2022). "On the other hand, SIRT1 can suppress tumor initiation, increasing genome stability and inhibiting inflammation at the pre-cancer stage." (PMID 35328633, 2022). "Evidences suggest that hypoxia is one of the hallmarks of malignant tumors and SIRT1 being a downstream target of HIF-1α is observed to be upregulated in OvCa, thereby conferring cancer stem cell-like properties." (PMID 35496046, 2022). "It has been reported that SIRT1 affects reactive oxygen species (ROS) and mitochondrial function, which regulates cancer cell growth and apoptosis, such as MCF-7 cells." (PMID 36552538, 2022). "Sirtuin family proteins are class Ш histone deacetylases (HDACs) and the best known is the well-described role of SIRT1 in cancer and ageing." (PMID 35853978, 2022). "Although it has received much attention, the role of SIRT-1 in cancer growth is still controversial." (PMID 34986886, 2022). "Among its various functions, studying the interactome of SIRT1 and revealing its detailed mechanisms would be helpful for understanding its important functions in diseases and cancers." (PMID 36552538, 2022).
cancer (continued). "The Sirtuin 1 (SIRT1) gene is the most frequently studied family member of all SIRTs in various types of cancer, including GC." (PMID 36499440, 2022). "SIRT1, the most extensively characterized family member, has also been demonstrated to be involved in cancer progression." (PMID 35548580, 2022). "Several recent studies have provided evidence that SIRT1 serves as a tumor suppressor and that overexpression of SIRT1 attenuates cancer formation both extends lifespan and inhibits cancer formation." (PMID 35326523, 2022). "In this cancer, SIRT1 deacetylates HIF-1α at lysine 674 inhibiting the interaction between this transcriptional factor and p300, thereby maintaining an epithelial-like phenotype." (PMID 35745656, 2022). "SIRT1 has been reported to belong to the sirtuin family, resist metabolic disorders, cancer, and cardiac stress (Cantó and Auwerx, 2012) and block the muscle-specific UPS proteins MAFbx and MuRF-1." (PMID 35370668, 2022). "In this study, we have deeply investigated the therapeutic effect of elaiophylin on LADC and found elaiophylin exerts its anti-cancer effect though inhibiting mitophagy and oxidative stress and targeting SIRT1/Nrf2 signaling." (PMID 36497294, 2022). "Results of ChIP assay then showed that the enrichment level of FOXQ1 in cancer tissues in SIRT1 promoter region was much higher than that in adjacent normal tissues." (PMID 35183223, 2022). "SIRT1 is also upregulated in hepatocellular carcinomas (HCCs), where it increases cancer cells’ invasiveness and metastatic potential through the activation of SNAIL, TWIST, and VIMENTIN, and decreases the expression of E-cadherin." (PMID 35745656, 2022). "Several studies have highlighted the role of SIRT1 in EMT activation or repression based on different cancer histotypes." (PMID 35745656, 2022). "It has been considered to act dualistically either suppressing or promoting cancer, depending on the temporal and special distribution of different Sirt1 upstream and downstream factors." (PMID 34870752, 2022). "The role of SIRT1 in cancer and in therapy response remains a controversial topic, while it contributes to attenuation of metabolic disorders." (PMID 35890085, 2022). "Heterozygous deletion of SIRT1 induces c-Myc expression, enhancing glutamine metabolism and subsequent proliferation, autophagy and cancer formation." (PMID 36581622, 2022). "Other studies, on the other hand, have shown that inhibiting or decreasing SIRT1 can inhibit cancer cell proliferation." (PMID 36460715, 2022). "Seven members of the family have been identified (SIRT1-7), among which SIRT1 was the first sirtuin to be shown to be involved in cancer." (PMID 36671446, 2022). "In the present study, we are the first to report the anti-cancer effect of Elaiophylin in in vitro, ex vivo and in vivo UM models, which is mediated through mitophagy inhibition, and the modulation of SIRT1-FoxO3a signaling axis." (PMID 35387119, 2022). "SIRT1 is upregulated in several cancers, and its overexpression can enhance tumor growth and promote cell survival." (PMID 35163511, 2022). "SIRT1 can function as a tumor promoter or suppressor, depending on their expression levels in cancer cells, actions on cell proliferation and death, as well as their effects on oncogenic and tumor-suppressive proteins." (PMID 36387211, 2022).
cancer (continued). "Conversely, SIRT1 is highly activated in cancer cells, and melatonin blocks SIRT1, thereby inhibiting cell proliferation and exerting a tumor suppressing effect." (PMID 36225557, 2022). "The protein deacetylase Sirt1 plays a broad role in anti-aging, anti-cancer, anti-inflammatory and other beneficial cardiovascular effects." (PMID 35342358, 2022). "Keeping in pace with the detection of tumor markers, we have assessed by performing IHC the expression of metabolic marker, silent information regulator 1 (sirtuin 1/SIRT1), since dysfunction in metabolic reprogramming is one of the hallmarks of cancer." (PMID 35496046, 2022). "The SIRT1 agonist resveratrol acts as an antioxidant enzyme in alcohol-aflatoxin B1-induced HCC and inhibits cancer cell proliferation through SIRT1-mediated modification of PI3K/AKT signaling." (PMID 36430361, 2022). "Among the phosphoproteins, we validated four enzymes associated with cancer and present only in sEVs isolated from MCF7 and MDA-MB-231 cell lines: ATP citrate lyase (ACLY), phosphofructokinase-M (PFKM), sirtuin-1 (SIRT1), and sirtuin-6 (SIRT6)." (PMID 35203617, 2022). "The upregulation of SIRT1 by for Forkhead Box Q1 (FOXQ1) contributes to CRC survival inducing cancer cell radio-resistance and cell stemness." (PMID 35328633, 2022). "On the other hand, other EPHs (Bifurcaria bifurcata, Codium decorticatum) exhibited high SIRT1 inhibition values, and several studies showed that decreasing SIRT1 can inhibit cancer cell proliferation." (PMID 36460715, 2022). "The level of expression of SIRT1 has been demonstrated to be elevated in normal and cancer stem cells (CSC), compared to their differentiated counterparts." (PMID 36429035, 2022). "For example, different SIRT1-induced modifications for DNA integrity preservation have been described both in normal and in cancer cells." (PMID 35956321, 2022). "In this review, we discuss the current information on the mechanistic roles of SIRT1–7 and their downstream effects (tumor promotion or suppression) in cancers of the breast and prostate." (PMID 36291902, 2022). "The protective activities of curcumin against the growth of cancer cells are mediated by modulating oxidative stress, regulating fibrosis, SIRT1 activation, and inducing cellular apoptosis." (PMID 36143462, 2022). "It has been suggested that melatonin is directly involved in controlling SIRT1, which inhibits its activity in cancer cells, in contrast to its stimulatory action in normal cells." (PMID 36009340, 2022). "SIRT1 has a dual role; it can promote or inhibit cancer depending on the cellular context, specific signaling pathways, or specific cancer targets." (PMID 36430164, 2022). "Its expression level has been reported to increase in a number of tumor types; however, some cancers, such as breast and ovarian, show down-regulated levels of SIRT1." (PMID 35327946, 2022). "SIRT1 is highly expressed in human squamous cell carcinoma, basal cell carcinoma and other tumor tissues, which is involved in the process of cancer cell growth." (PMID 34384029, 2021). "Many small molecule inhibitors of SIRT1 have been developed and exhibit encouraging anti-tumor effects against various cancers, including BRCA." (PMID 34413268, 2021). "Sirtuin 1 (Sirt1) and Dnmt1 DNA (cytosine-5)-methyltransferase 1 (DNMT1) affect both cell proliferation and differentiation, being associated with several cancer processes, and regulating cell cycle-associated genes." (PMID 34359925, 2021).
cancer (continued). "The elevated SIRT1 activity also facilitates the deacetylation of FOXOs, which are transcription factors that have major impacts on longevity and cancer." (PMID 34016143, 2021). "In some cancer types, SIRT1 is upregulated and therefore considered as a target for specific inhibitors." (PMID 34885146, 2021). "More than a dozen miRNAs have been found to affect Sirt1 in cancer and cardiovascular diseases, some of which indirectly regulate Sirt1 expression and activity, although most directly act on its mRNA." (PMID 33159388, 2021). "Among all, Sirt1, Sirt6 and Sirt7 was demonstrated to involve in DNA damage repair, the over-activation of which accounts mainly for radioresistance of cancer 19,20." (PMID 34405009, 2021). "These analyses show that SIRT1 and CUL4B have similar expression trends in a variety of cancers, further supporting the idea that the SIRT1/CRL4B complex plays key roles in cancer as an organic whole." (PMID 34163012, 2021). "Identifying new regulators of SIRT1 activity would be helpful in understanding the regulatory network of SIRT1 and its biological relevance in cancer development and tumor therapeutics." (PMID 34471223, 2021). "The NAD-dependent protein deacetylase, SIRT1, belongs to the sirtuin family and it performs a wide variety of functions in resisting metabolic disorders, cancer and cardiac stress etc.." (PMID 33935745, 2021). "Curcumin and resveratrol elicited beneficial effects on fast- and slow-twitch limb muscle phenotypes in cachectic mice through sirtuin-1 activation, attenuation of atrophy signaling pathways, and proteolysis in cancer cachectic mice." (PMID 34443492, 2021). "The several functional characters of SIRT1, particularly the argument for both tumor promoter and tumor suppressor roles, have given glamor attention in SIRT1 for cancer treatment." (PMID 33705642, 2021). "Butyrate is produced by bacterial fermentation of fibers in the intestine and has been shown to inhibit SIRT1, showing antitumor effects on various cancers." (PMID 35096835, 2021). "As an activator of Sirt1, resveratrol (Res) is a natural anti-aging agent and has shown good anti-cancer and anti-aging effects." (PMID 33562281, 2021). "Changes in Sirt1 expression are critical in several diseases, such as cardiovascular diseases, metabolic syndrome, cancer, neurodegeneration, and infertility." (PMID 34575829, 2021). "This discrepancy is explained by the fact that SIRT1 is an accessory factor in the cellular circadian oscillator machinery and that cancer cells have to silence those circadian oscillator components that possess tumor suppressing properties." (PMID 34279445, 2021). "SIRT1 plays important roles in diverse cellular processes including oxidative stressalleviation, oncogenesis, aging and cancer progression." (PMID 34096221, 2021). "SIRT1 plays crucial roles in many cellular events, including aging, cancer, and cellular reprogramming." (PMID 34471223, 2021). "In mammals, SIRT1 prevents tumorigenic transformation by epigenetically silencing cancer-promoting genes or leukemic genes." (PMID 33539925, 2021). "The impact of SIRT1 on cancer development, prognosis, or invasion has been studied in several studies." (PMID 34942940, 2021). "Both antagonistic mechanisms, i.e., SIRT1 activation and inhibition, have been proposed in cancer therapy." (PMID 33669990, 2021).
cancer (continued). "Researchers in South Korea led by Sang Yoon Kim and Seong Who Kim at the University of Ulsan, Seoul, investigated the role of the proteins Sirt6, Sirt1 and MDM2 in controlling the death of cancer cells caused by chemicals called reactive oxygen species (ROS)." (PMID 33727672, 2021). "Our study aimed to investigate function and mechanism of miR-373 in proliferation and apoptosis ofpancreatic cancer (PC) cells by regulating NAD+-dependent histone deacetylase sirtulin 1 (SIRT1)." (PMID 34096221, 2021). "Second, Sirt1 activity is regulated by physical interaction with other proteins such as DBC1 (Deleted in Breast Cancer 1)." (PMID 34216621, 2021). "As shown in this study, Sirt1 is likely to aggravate malignant development: we observed an increase in ROS expression, leading to an elevated frequency of cancer cell death, when Sirt1 was downregulated by Sirt6." (PMID 33727672, 2021). "Overexpression of Sirt1, the mammalian homolog of Sir2, has been described to protect mice from aging and cancer." (PMID 34216621, 2021). "Among them, SIRT1 is the most well-studied, and has a critical role in cancer because it inhibits glycolysis and stimulates fatty acids." (PMID 34579773, 2021). "Recent studies have confirmed that regulation of SIRT1 expression can affect the malignancy of various cancer cells in vitro and in vivo." (PMID 34934771, 2021). "Sirtuin 1 biological role in cancer is complex and depends on its targets in specific signaling pathways." (PMID 33917352, 2021). "The evidence from numerous studies proves sirtuin 1 significance in both chronological and premature aging as well as its dual role in cancer development." (PMID 33917352, 2021). "Sirtuin 1 (SIRT1) is associated with the most complex physiological processes, including metabolism, cancer onset, and aging." (PMID 33889076, 2021). "To further gain insight into the mechanism by which SYT8 and SIRT1 mediated cancer progression, we investigated the orphan NR, ERRα, which was identified as a SIRT1 interactor by bioinformatics analysis." (PMID 34907162, 2021). "It has been reported that histone deacetylase SIRT1 which can eliminate the generation of ROS in cancer cells." (PMID 33345272, 2021). "Resveratrol treatment mimics the protective effect of caloric restriction against cancer by inducting Sirt1." (PMID 33430318, 2021). "SIRT1 is known to be a critical antiaging molecule, and a decline in SIRT1 expression and activity during aging is correlated with severe disorders such as cardiovascular diseases, neurodegenerative disorders and cancer." (PMID 34073102, 2021). "Although regulation of SIRT1 by circRNAs has been elucidated in some cancers and diseases, our study was the first to uncover the circRNA-mediated regulation of SIRT1 in CH." (PMID 34759275, 2021). "This SIRT1-dependent mechanism enables cancer cells to create the suitable extracellular microenvironment for the expansion of themselves." (PMID 33390835, 2021). "Similar to Myc, expression of SIRT1 was found to correlate with aggressive tumors, and to promote cancer progression in BC by modulating Akt activity, making it another potential therapeutic target." (PMID 34959644, 2021).